IL10 (interleukin 10)
Diseases named in the same sentence as IL10 in open-access papers (continued):
Sharing a sentence is not in itself a finding about the gene and the disease.
Autoimmunity (continued). "We and other demonstrated the ability of IL-10 or IL-10-inducing agents in combination with immunosuppressive treatments to generate Tr1 cell in in vivo models of autoimmunity or allogeneic transplantation." (PMID 29497421, 2018). "B10 cells serve as negative regulator of immune responses solely attributed to IL-10 production in B cells, which have been found to dampen T-cell-mediated inflammation, regulate the autoimmunity and maintain immune system homeostasis." (PMID 30355335, 2018). "CD46 is a co-stimulatory factor for the development of T-helper cells, and works through IL-10 release, suppressing immune responses to prevent autoimmunity." (PMID 30133498, 2018). "Previous studies have reported the skewing of T helper responses or induction of IL-10-producing type 1 Treg cells after DNA vaccination; these effects inhibit the development of autoimmunity." (PMID 29894515, 2018). "Tr1 cells dampen autoimmunity and inflammation by promoting expression of the immunosuppressive cytokine IL-10." (PMID 30442091, 2018). "In this regard, regulatory B (Breg) cells producing IL-10 inhibit autoimmunity and allograft rejection and promote tumor growth." (PMID 29212210, 2017). "In SLE animal models, continuous administration of anti-IL-10 antibody to NZB/W F1 mice delayed the onset of autoimmunity." (PMID 28380214, 2017). "In conclusion, as one of the suppressive T cell subsets, TR1 cells have been described to regulate inflammation, graft-versus-host disease and autoimmunity by producing IL-10." (PMID 28993775, 2017). "Treg is a subset of CD4+ T cells that maintain peripheral tolerance and suppress antigen specific immune responses by secreting transforming growth factor-β (TGF-β), interleukin-10 (IL-10), and IL-4 to inhibit autoimmunity." (PMID 27777959, 2016). "Consistent with the finding that IL-12 is an important driver of Blimp-1-dependent Tr1 cell differentiation in autoimmunity, we found that Blimp-1 and IL-10 expression by IFNγ-producing CD4+ T cells from L. donovani-infected mice required IL-12." (PMID 26765224, 2016). "The immunosuppressive cytokine Interleukin (IL)-10 counteracts hyperactive immune responses and critically controls immune homeostasis in infectious and autoimmune disorders." (PMID 27611574, 2016). "For example, LAG3 is a CD4 receptor homologue that by interfering with MHCII on APC upon antigen exposure inhibits the function and expansion of memory T cells decreasing IL-17 and increasing IL-10 secretions, this way preventing autoimmunity in mice." (PMID 27256343, 2016). "IL-10-producing regulatory B cells (B10 cells) areable to downregulate inflammation and autoimmunity, and one proposed mechanism isthe inhibition of Th1 differentiation." (PMID 26602597, 2015). "A recent murine study identified a different IL-10 independent mechanism through which B cells can regulate autoimmunity." (PMID 25002862, 2014). "Of note IL-10, which is known to play a suppressive function in several autoimmune disorders including EAE, was also increased in Was−/− mice." (PMID 24466296, 2014). "This key role of B cell derived IL-10 in controlling T cell mediated autoimmunity was supported in several studies." (PMID 25002862, 2014). "All together, we define a novel role of Tfh cells in immune regulatory actions to promote production of the immunosuppressive cytokine IL-10, which extends the existing recognization that Tfh cells merely induce humoral responses and augment autoimmunity." (PMID 24551101, 2014). "IL-10 can enhance B cell survival, proliferation, maturation, and antibody production, implying a possible role of IL-10 for autoimmunity during ADE of DENV infection." (PMID 23800014, 2013). "Tregs produce IL-10, which is able to inhibit, either directly or indirectly, effector T cell activity during infection, autoimmunity, and cancer." (PMID 23843861, 2013).
Autoimmunity (continued). "A set of key interleukins, namely pro-inflammatory IL-6, immunoregulatory IL-10, anti-inflammatory IL-13, and autoimmunity-related IL-17, were assayed by ELISA." (PMID 24236103, 2013). "Investigating these connections, IL-6, IL-17, IL-10 and IL-1 cytokine activation has been demonstrated suggesting the activation of shared innate pathways in autoimmunity." (PMID 24069364, 2013). "For example, B7 expression by B cells is required for mediating recovery in murine models of autoimmunity by mediating peak expression of IL10 and Foxp3." (PMID 23755918, 2013). "Interleukin-10 (IL-10) producing B cells, also known as regulatory B (Breg) cells, play a key role in controlling autoimmunity." (PMID 22315945, 2012). "In particular, B10, a potent regulatory B-cell subset within the rare CD1dhiCD5+ B-cell subset of the spleen, has been shown to regulate acute inflammation and autoimmunity through the production of IL-10." (PMID 23194300, 2012). "It even suggests that in certain inflammatory models IL-10 secreting Bregs can be apical to regulatory T cells in prevention of autoimmunity and the maintenance of tolerance." (PMID 22315945, 2012). "Protective contributions of regulatory B cells in mouse models of autoimmunity and allergy include B cell-intrinsic IL10 production, often corresponding with innate-like (MZ B and B1 B cell) phenotypes." (PMID 23087687, 2012). "Other studies demonstrated that IL-10-producing Bregs function to downregulate autoimmunity and allergic disorders by inducing Tregs." (PMID 23071588, 2012). "In the context of autoimmunity, the overlapping EAE phenotypes of IL-27, IL-10, and IFNAR deficient mice suggest that these molecules are probably functionally linked in the regulation of Th17 development." (PMID 22163016, 2011). "Tr1 cells are regulatory T cells that do not express Foxp3 and suppress tissue inflammation, graft-versus-host disease and autoimmunity in an IL-10 dependent manner." (PMID 21886804, 2011). "Experimental investigations showed that anti-mouse IL-10 mAbs increased survival in mice and protected from development of lupus-like autoimmunity BALB/c mice given continuous IL-10 administration." (PMID 27713252, 2010). "It has been reported that treatment with anti-IL-10 antibody delayed onset of autoimmunity in (NZW/NZB)F1 mice and led to a reduction in disease activity." (PMID 20573280, 2010). "However, some deleterious effects of dysregulated IL‐10 have been described, such as the promotion of autoimmunity and elevated serum levels have been observed in patients with severe Guillain–Barré Syndrome." (PMID 41556482, 2026). "Research also indicates that systemic overexpression of IL‐10 in NOD mice suppresses autoimmunity." (PMID 40903907, 2025). "Elevated levels of IL-6, TNF-α, and IL-1β contribute to chronic inflammation and antibody production, whereas decreased production of IL-10 may explain the failure to suppress autoimmunity in ITP." (PMID 40922302, 2025). "VDR binds to the IL-10 promotor and increases IL-10 synthesis, possibly reducing autoimmunity, whereas vitamin D has been demonstrated to decrease the formation of lupus-associated autoantibodies, like anti-nuclear antibody (ANA), irrespective of its effect on B cell differentiation." (PMID 41157255, 2025). "Additionally, B cells have been shown to be able to provide IL-10-mediated protection against autoimmunity in mice." (PMID 40095800, 2025). "In contrast, IL-10 acts as a key anti-inflammatory cytokine that promotes immune tolerance by suppressing innate immune activation, inhibiting pro-inflammatory cytokine release, impairing antigen presentation, and mitigating autoimmunity." (PMID 41373936, 2025). "On the other hand, increased induction of IL-10 by Escherichia coli strain Nissle 1917-treated mice may be a preventive mechanism of inflammation and autoimmunity." (PMID 40273120, 2025).
Autoimmunity (continued). "The dynamic balance between Th17 and Treg cells is essential for maintaining immune homeostasis: Treg cells expressing IL-10 and TGF-β establish pregnancy tolerance, while Th17 cells producing IL-17, IL-21, and IL-22 are associated with pregnancy loss and autoimmunity." (PMID 40894398, 2025). "One of the first reports on the possible role of the mTOR pathway in the regulation of macrophage function in autoimmunity demonstrated the dependence of IL-10 secretion by macrophages cultured with synovial T cells isolated from patients with rheumatoid arthritis on p70 S6 kinase." (PMID 40806725, 2025). "Conversely, literature reviews suggest that reductions in Tregs and diminished IL-10 secretion in BD may account for the elevated incidence of autoimmune disorders." (PMID 39220183, 2024). "IL10 provides positive feedback by promoting the expansion of IL10-secreting regulatory T cells, which are critical for immune regulation in conditions like autoimmunity, chronic inflammation, and transplantation." (PMID 39765683, 2024). "In contrast, the red M7 module was dominated by immune-related terms such as cytokine–cytokine receptor interaction; interleukin signaling (i.e., IL-17 and IL-10); inflammation; and decreased production of antibodies, autoimmunity, and immune cell proliferation and migration." (PMID 37108604, 2023). "In summary, IL-10 combined with regenerative therapy may offer fresh perspectives for inflammation and immune regulation, especially at trauma-induced autoimmunity after SCI." (PMID 37492521, 2023). "Deficiencies in number and/or function of IL-10 producing, suppressive B cells or Bregs have been found both in mouse models of SLE and human SLE patients suggesting an important role for Bregs in controlling autoimmunity." (PMID 38155972, 2023). "The diminished levels of IL-10 in patients with CVID that are sensitive to PKAI activity might influence autoimmune disorders and defects in B cells." (PMID 36834508, 2023). "Treg suppresses inflammation and autoimmunity by utilizing IL-10." (PMID 36408259, 2022). "IL-10, producing regulatory B (Breg) cells, restrains inflammation by promoting differentiation of immunoregulatory and pro-inflammatory T cells and is responsible for controlling autoimmunity." (PMID 35270791, 2022). "Indeed, they can negatively regulate T-cell immune responses to maintain self-tolerance and prevent autoimmunity by secreting anti-inflammatory mediators such as IL-10, IL-35, and transforming growth factor β (TGF-β)." (PMID 35935985, 2022). "Notably, BA protects against autoimmunity by increasing IL-10+ Bregs and by supporting antibody responses both in the intestine and systemically." (PMID 35333906, 2022). "Additionally, these LiNKTR1 cells suppress autoantigen presentation, and recognize CD1d expressed on conventional B cells to induce IL-10+IL-35-producing regulatory B (Breg) cells, leading to the suppression of liver and pancreas autoimmunity." (PMID 35672409, 2022). "Based on the differences in CD19+CD5+ B cells and serum IL-10 between patients and HC, supplementary assessments could be of value in clarifying their roles in autoimmunity." (PMID 35031055, 2022). "Next, some investigators have proposed that IL-10-producing regulatory B cells may be important in autoimmunity." (PMID 35095887, 2021). "In the last years, an emerging role for Breg cells arouses more and more interests, which may inhibit the proinflammatory response, mostly by production of IL-10 cytokine, which exerts suppressive effects of autoimmunity." (PMID 34422046, 2021). "Interestingly, human ASCs were reported to induce the expansion of IL-10-producing Breg cells and significantly ameliorated autoimmunity in a murine model of SLE, showing the beneficial role of this mechanism in vivo." (PMID 35095547, 2021). "Moreover, the SCFA valeric acid has been reported to suppress autoimmunity by increasing the expression of IL-10 and suppressing Th17 cells." (PMID 33748287, 2021).
Autoimmunity (continued). "TGFβ-1 and IL-10 cytokines have a central role in maintaining the immune balance by limiting immune reactions and promoting additional inducible regulatory T cell differentiation (iTreg), thus preventing uncontrolled inflammation and/or autoimmunity." (PMID 34071714, 2021). "IL‐10‐producing regulatory B cells (Bregs) are a more recently discovered type of B cell which are immunomodulatory and critical in regulating immune responses involved in inflammation, autoimmunity, and cancer." (PMID 33506633, 2021). "IL-10 signalling has been shown to play a critical role in restraining effector T cell responses in the context of resolving immune responses to pathogens and preventing the development of autoimmunity." (PMID 33704423, 2021). "Nonetheless, IL-21- and CD40 dependent cognate interactions with T cells are also required for IL-10-producing Breg cells to optimally suppress inflammation and autoimmunity, and adding CD40L to the LPS cultures increased IL-10 producing B-cell frequencies in the health controls." (PMID 34867940, 2021). "We propose that loss of IL-10 signaling in CD4+ T cells promotes non-neuroprotective autoimmunity after FNA." (PMID 32303238, 2020). "Future studies will focus on understanding the dichotomy between different TLR stimulation signals and the induction of IL-10 and how this could be exploited for the treatment of autoimmunity." (PMID 32849556, 2020). "Gain of IFNγ production and reduction in IL-10 production by CD8 Tregs in PE IL-2Rα-KO mice may allow earlier advancement of autoimmunity." (PMID 33319815, 2020). "Inhibiting the activation and expansion of pathogenic cells through IL-10 is the main function of Bregs; remarkably, a lack of Bregs cells is involved in autoimmunity, and a functional deficiency of IL-10+ B cells occurs in allergic airway inflammation." (PMID 30818819, 2019). "In addition to Treg, regulatory B cells (Breg) have been widely recognized as negative regulators of immune responses controlling autoimmunity and inflammation in suppressing pathological immune responses primarily through the secretion of IL-10." (PMID 31120872, 2019). "Consequently, this IL-10 producing immature B cell population was shown to influence and modulate immune responses during autoimmunity, HIV infection and graft-versus-host disease." (PMID 31120872, 2019). "It has been noted that activated B cells produce interleukin-10 (IL-10) to inhibit autoimmunity by suppressing pathogenic T cells and HIF-1α deficiency results in an increased B1-like cell population which further causes autoimmunity." (PMID 30413999, 2019). "The increase in effector T lymphocytes demonstrated here may be due to the depletion of regulatory B lymphocytes, which would normally downregulate inflammation and autoimmunity through IL-10." (PMID 31647850, 2019). "CD4+ CD25+ Foxp3+ regulatory T cell (Treg), another subtype of CD4+ T cell, is essential for preventing autoimmunity and maintaining lymphocyte homeostasis by contacting or releasing inhibitory cytokine like IL-10 and TGF-β on other immune cells during chronic inflammatory disease." (PMID 30800170, 2019). "While vitamin D has been shown to reduce the production of lupus-related autoantibodies, such as anti-nuclear antibody (ANA), independent of its impact on B cell differentiation, VDR binds to the IL-10 promotor and enhances IL-10 production, potentially alleviating autoimmunity." (PMID 30103428, 2018). "In addition, vitamin D represses Th1 and Th17 responses and increases the production of T-regulatory cells, interleukin-10 (IL-10) and NK cells, all processes that are likely involved in the pathogenesis of autoimmunity." (PMID 29659559, 2018). "The serum levels of pro-inflammatory and immunomodulatory cytokines such as IL-1β, IL-6, IL-8, IL-10, IL-17, and IL-15 were used as secondary study endpoints as they provide a strong evidence of the efficacy of the hMSCs administration inmodulating autoimmunity." (PMID 30254638, 2018).
Autoimmunity (continued). "Recent research reported that MDSCs could induce IL-10-producing B cells via inducible nitric oxide synthase (iNOS) in vitro and ameliorate autoimmunity in a murine model of SLE via expansion of Bregs and reduction of effector B cells." (PMID 29371592, 2018). "Thus, we characterized a B cell-intrinsic microRNA pathway that inhibits the differentiation of IL-10+ Breg cells and promotes autoimmunity." (PMID 29212210, 2017). "IL-10 production by Th17 cells is critical for limiting autoimmunity and inflammatory responses." (PMID 28300844, 2017). "Since we had previously shown that the CD5+ B cells in B6.NZBc4 mice have a regulatory function and produce IL-10, we questioned whether knockout of IL-10 could uncover autoimmunity." (PMID 26964093, 2016). "The importance of IL-10 production by DCs in the induction of tolerance has been demonstrated, as DCs genetically modified to express IL-10 exhibit suppressive effects in models of alloreactivity and autoimmunity." (PMID 27172902, 2016). "In this paper, we aimed to further resolve the genetics that leads to expansion of these two innate-like populations through the creation of additional sub-congenic mice and to characterize the role of IL-10 in the suppression of autoimmunity through the generation of IL-10 knockout mice." (PMID 26964093, 2016). "Finally, co-culture of MSCs with splenic B cells induced regulatory B cells producing IL-10 that ameliorated autoimmunity and Ab synthesis." (PMID 26840058, 2016). "When antigen presenting cells are stimulated with Toll like receptor ligands, such as TLR4 ligand LPS, they produce both IL-10 and IL-12; as the secretion of IL-10 after TLRs stimulation is a feedback mechanism to prevent excess immune responses to avoid autoimmunity." (PMID 27100390, 2016). "IL-27 suppresses effector Th17 cells and promotes the generation of type 1 regulatory T (Tr1) cells, which, in turn, could dampen autoimmunity and tissue inflammation by secreting the immunosuppressive cytokine IL-10." (PMID 26636339, 2015). "Thus, B cells are able to suppress autoimmunity in different animal models either through the production of IL10 or TGFβ as well as by cytokine independent functions." (PMID 26047509, 2015). "Finally, the clearance of apoptotic cells requires the production of IL-10 to prevent the induction of autoimmunity." (PMID 25093822, 2014). "Previous findings have reported an exacerbated disease phenotype and enhanced mortality in IL10 gene-deficient lupus-prone MLR mice, and administration of rIL-10 reduced autoantibody production, highlighting the importance of IL10 in down modulating autoimmunity." (PMID 23755918, 2013). "The implication of IL-10 in DENV-induced autoimmunity needs further study." (PMID 23800014, 2013). "CD5+ B cells are reported to produce IL-10 with immunoregulatory property, which may explain a role of leptin in autoimmunity." (PMID 23343052, 2013). "IL-10- producing B cells play an important role in controlling autoimmunity, such as in EAE, an animal model of MS, and in a systemic lupus erythematosus (SLE)-like disease that develops in the Lyn-deficient mouse and during murine cytomegalovirus (MCMV4) infection." (PMID 22969768, 2012). "In addition, IL-10-producing B cells, also known as regulatory B cells (Bregs), play a key role in controlling autoimmunity." (PMID 23125486, 2012). "It was possible that the induction of IL-10-dependent tolerogenic environment by multiple DC transfers might play a crucial role in the progression of autoimmunity in MRL/lpr mice." (PMID 23300516, 2012). "The ability of IL-27 to induce IL-10 is important to suppress TH17 cell–mediated autoimmunity." (PMID 22969768, 2012). "This study described a novel autoregulatory property of B-1P cells mediated by B-1P cell derived IL-10, which may affect the function of B-1P cells in infection and autoimmunity." (PMID 20625435, 2010).